ICOS (inducible T cell costimulator)
Description:
Stimulatory receptor expressed in activated or antigen-experienced T-cells that plays an important role in the immune response. Upon binding to its ligand ICOSL expressed on antigen presenting cells (APCs), delivers costimulatory signals that enhances all basic T-cell responses to a foreign antigen, namely proliferation, secretion of lymphokines including IL10, up-regulation of molecules that mediate cell-cell interaction, and effective help for antibody secretion by B-cells. Also acts as a costimulatory receptor critical for the differentiation of T follicular regulatory cells upon immune challenges such as viral infection. Mechanistically, potentiates TCR-induced calcium flux by augmenting PLCG1 activation and actin remodeling (By similarity). In addition, activates PI3K signaling pathways independently of calcium flux. Essential both for efficient interaction between T and B-cells and for normal antibody responses to T-cell dependent antigens. Prevents the apoptosis of pre-activated T-cells. Plays a critical role in CD40-mediated class switching of immunoglobin isotypes (By similarity).
Synonyms: CD278; AILIM; CVID1
Tractability: Antibody: a drug acting on it is in phase 2 or 3 trials; UniProt places it where antibodies can reach, with high confidence; its Gene Ontology location is reachable by antibodies, with high confidence; UniProt predicts a signal peptide or a membrane-spanning region; the Human Protein Atlas places it where antibodies can reach. PROTAC: a small molecule that binds it is known.
Gene: Protein-coding gene on chromosome 2 (203,936,763 to 203,961,577, forward strand). Ensembl gene ENSG00000163600.
Subcellular location: Cell membrane (Isoform 1); Secreted (Isoform 2)
Subcellular location (Human Protein Atlas): Plasma membrane; Actin filaments
Pathways (Reactome):
Disease: Constitutive Signaling by Aberrant PI3K in Cancer; Nuclear events stimulated by ALK signaling in cancer
Signal Transduction: PI5P, PP2A and IER3 Regulate PI3K/AKT Signaling; PIP3 activates AKT signaling
Immune System: Co-stimulation by ICOS
Gene Ontology:
Molecular function: protein binding; signaling receptor activity
Biological process: T follicular helper cell differentiation; cell-cell adhesion; immune response; T cell costimulation; T cell tolerance induction
Cellular component: plasma membrane; external side of plasma membrane; extracellular region
Genetic constraint (gnomAD): Loss-of-function variants: 9 observed, 12.33 expected, observed/expected ratio (o/e) 0.73, 90% interval 0.44 to 1.27. The upper end of that interval is the gene's LOEUF score, 1.27, which puts it in group 5 of 6, group 1 being the genes least tolerant of losing a copy. Missense variants: 160 observed, 192.32 expected, observed/expected ratio (o/e) 0.83, 90% interval 0.73 to 0.95. Synonymous variants: 70 observed, 66.23 expected, observed/expected ratio (o/e) 1.06, 90% interval 0.87 to 1.29.
Gene-disease validity (ClinGen):
ClinGen rates the evidence that ICOS causes each of these diseases.
common variable immunodeficiency (autosomal recessive): Definitive.
Homologues: Orthologues: chimpanzee ICOS (99% identical), macaque ICOS (96% identical), rabbit ICOS (78% identical), pig ICOS (74% identical), dog ICOS (71% identical), guinea pig ICOS (69% identical), mouse Icos (68% identical), rat Icos (66% identical), tropical clawed frog icos (28% identical).
Diseases named in the same sentence as ICOS in open-access papers:
ICOS is named in the same sentence as 264 diseases in open-access papers, as found by Europe PMC text mining. Sharing a sentence is not in itself a finding about the gene and the disease. The quoted sentences say what the papers report.
melanoma (59 papers, 2012 to 2025). A malignant, usually aggressive tumor composed of atypical, neoplastic melanocytes. "Downregulation of VISTA, IDO1 and ICOS was associated with melanomas that gave rise to distant metastases including brain." (PMID 40621453, 2025). "ICOS is also predominantly expressed on tumor-associated Tregs in several cancers, including breast cancer and melanoma, while ICOSL is found on pDCs in cancers like breast, ovarian, and gastric cancers." (PMID 41180156, 2025). "We found a cell type-specific methylation pattern and locus-specific correlations and associations of CpG methylation with ICOS mRNA expression, immune infiltration, melanoma differentiation, prognosis, and response to ICB." (PMID 37259155, 2023). "When viewed in combination, these studies demonstrate that melanoma lung metastasis is associated with significantly suppressed expression of T cell co-stimulators including ICOS, ICOSL and CD28." (PMID 36618349, 2022). "In spite of this, immunologists, both domestically and internationally, are of the opinion that immune function of ICOS on tumors can be induced in NK cells, and the survival rate of melanoma cells is closely associated with the expression of ICOS." (PMID 29316975, 2018). "Finally, recent data obtained on melanoma and breast cancer indicated that there is an association between the expression of ICOS and the production of immunosuppresive interleukin IL-10 in Tregs that results in suppression of T cells and dendritic cells." (PMID 29285252, 2017). "For patients with melanoma 9 gastric cancer 11, and glioma 36, higher ICOS expression predicted poorer survival." (PMID 38616999, 2024). "The expression of ICOS by tumor microenvironment (TME) Tregs is associated with poor prognosis in many solid cancers, such as melanoma 9, breast cancer 10 and gastric cancer." (PMID 38616999, 2024). "ICOS is found in T regulatory cells in melanoma patients, and cells with high expression can induce diverse immune responses in responder cells depending on activation signals and cytokines in the microenvironment." (PMID 39596506, 2024). "In the current study, we demonstrated that ICOS expression is regulated epigenetically via DNA methylation in melanoma." (PMID 37259155, 2023). "Our study identified ICOS DNA methylation and mRNA expression as promising prognostic and predictive biomarkers for immunotherapy in melanoma and points towards a hitherto undescribed role of ICOS in tumor cells." (PMID 37259155, 2023). "Of note, while most tumor cell show a cytoplasmic ICOS protein expression, we identified nuclear expression in hepatocytes and in melanoma cells which points towards a hitherto undescribed biological role of ICOS." (PMID 37259155, 2023). "The aim of this study was to investigate the epigenetic regulation of ICOS in melanoma by DNA methylation." (PMID 37259155, 2023). "These cells express PD1 and ICOS, similar to the ICOS+PD1+ Th1-like population that was expanded upon CTLA-4 blockade in melanoma patients." (PMID 37185301, 2023). "We therefore investigated the epigenetic regulation of ICOS via DNA methylation in more detail using the human A375 melanoma cell line." (PMID 37259155, 2023). "Of note, we also detected ICOS mRNA copies in few CD45− cells suggesting an ICOS mRNA expression by melanoma cells." (PMID 37259155, 2023). "We comprehensively investigate ICOS DNA methylation of specific CpG sites and expression pattern within the melanoma microenvironment with regard to immune correlates, differentiation, clinical outcomes, and immune checkpoint blockade (ICB) response." (PMID 37259155, 2023). "There are 12% of tumor-infiltrating lymphocytes expressing ICOS in melanoma, making it the most widely expressed costimulatory receptor in the tumor." (PMID 38127899, 2023). "Regarding expression by tumor cells, research has shown, that ICOSL is expressed by melanoma cells promoting the expansion of Tregs via ICOS/ICOSL signaling." (PMID 37259155, 2023).
melanoma (continued). "In melanoma, ICOS is the most expressed costimulatory receptor by tumor-infiltrating lymphocytes (TILs) with ICOS positivity found on regulatory, CD4+, and CD8+ T cells." (PMID 37259155, 2023). "To corroborate the publicly available TCGA data and evaluate cell-specific ICOS expression, we analyzed available melanoma, HNSCC, and NSCLC single-cell RNA-seq datasets." (PMID 37593752, 2023). "In the melanoma tumor microenvironment, ICOS was shown to be expressed on Tregs in tumor-infiltrating cells and was correlated with worse outcomes." (PMID 38127899, 2023). "Since both genes are co-located on chromosome 2 q33.2, are members of the CD28 immune checkpoint receptor family, are co-expressed in melanomas from the TCGA cohort, we expected co-expression of ICOS and CTLA4 in melanoma cell lines as well." (PMID 37259155, 2023). "Melanoma patients with enhanced expansion of ICOS+ Treg in blood following treatment had unfavorable clinical outcomes than patients with fewer ICOS+ Tregs." (PMID 36591244, 2022). "In human melanoma patients treated with high dose IL-2 therapy, the ICOS+ Treg population was the most expanded and the most proliferative lymphocyte population in the blood." (PMID 36591244, 2022). "For patients with melanoma, gastric and liver cancer, gynecological and breast cancer, and renal clear cell carcinoma, higher ICOS expression predicted much worse survival." (PMID 36276141, 2022). "ICOS has been widely reported as an important immune checkpoint among various cancers, including melanoma, gastrointestinal and liver cancer, gynecological cancer, breast cancer, renal clear cell carcinoma, and Merkel carcinoma." (PMID 36276141, 2022). "F42K, a mutant IL-2, induced a systematic decrease in the expansion of ICOS+ Treg cells, which promoted the expansion of NK cells and inhibited the tumor growth of melanoma more efficiently than wild-type IL-2." (PMID 35585567, 2022). "Poly(I:C) ameliorated melanoma- inhibition of ICOS, ICOSL and CD28 while abrogating the ability of B16 cells to stimulate CTLA-4." (PMID 36618349, 2022). "In mice bearing melanoma tumors, ICOS+ cells comprised a population of tumor-specific and Th1 cytokine-producing effector cells." (PMID 33777008, 2021). "Recent studies have shown that increased number of ICOS+ Tregs is found in various cancers, including melanoma and breast cancers." (PMID 34806028, 2021). "In this context, ICOS-L is expressed either by TA-plasmacytoid DC (pDC) in breast, ovarian and gastric cancers or by tumor cells in follicular lymphoma, acute myeloid leukemia or melanoma and plays a major role in the expansion of ICOS+ TA-Tregs." (PMID 33924428, 2021). "In support of this, proliferating ICOS + Tregs in melanoma patients treated with high-dose IL-2 have been reported to co-express high levels of CD73 and CD3940." (PMID 34650224, 2021). "This study investigates the role in tumor cell metastasis of the ICOS/ICOSL/OPN network, comparing the metastasizing capability of two variants of melanoma B16-F10 cells, respectively expressing high and low levels of ICOSL." (PMID 35052731, 2021). "Anti-PD1 and anti-CTLA4 treatments are effective in melanoma immune therapy and, intriguingly, their effectiveness is marked by increased expression of ICOS." (PMID 35052731, 2021). "The prognostic impact of ICOS expression is inconsistent across various tumour types (e.g., melanoma, colorectal cancer, breast cancer, gastric cancer, and renal cell carcinoma), and these clinical findings support the dual role of ICOS in carcinogenesis." (PMID 31882943, 2019). "More recently, it has been reported that anti-CTLA-4 therapy induces the expansion of melanoma-infiltrating ICOS+ TH1-like CD4+ T cells as well as exhausted-like CD8+ T cells." (PMID 29494517, 2018).
melanoma (continued). "On this point, it is known that mTORC1 drives expression of ICOS, a positive-acting T cell co-regulatory receptor, and that elevated expression of ICOS in melanoma patients receiving immune checkpoint therapy correlates with the most favorable outcomes." (PMID 30254983, 2018). "ICOS expression can be detected in a wide variety of tumor tissues, such as melanomas, lungs, ovaries, and colon, indicating that IOCS expression is correlated with the development and prognosis of several tumors." (PMID 29316975, 2018). "In patients with cancer, TReg cells are continuously exposed to tumour antigen (TA), either directly or through the tumour micro-environment which in turn, results in high levels of ICOS expression as has been demonstrated in melanoma and prostate cancer." (PMID 22666318, 2012). "Notably, in a melanoma lung metastasis model, ICOS knockout in Tregs has been reported to reduce tumor burden and increase Ly108+ Eomes+ CD8+ T cells, suggesting that ICOS-expressing Tregs inhibit cytotoxic T-cell maturation." (PMID 39684559, 2024). "In the immune microenvironment of CRC, unlike in melanoma, ICOS expression is associated with high expression of CTLA‐4 and PD‐1 on lymphocytes." (PMID 38506253, 2024). "It has been reported that type I IFN is involved in the expression of ICOS‐L on pDCs in psoriatic lesions and melanoma, which suggested that pDCs may be involved in Treg activation through ICOS/ICOS‐L interaction." (PMID 38506253, 2024). "More recent research has linked ICOS to the functional advantage of CD8+ antigen-specific T-cell clones isolated from melanoma patients through activation of AKT in the absence of CD28, suggesting a potential role in cancer immunotherapy." (PMID 39684559, 2024). "Interestingly, in the early nineties, nuclear EGFR expression has firstly been described in rat hepatocytes (reviewed in:) which is in-line with our finding of nuclear ICOS expression in adjacent hepatocytes from a melanoma liver metastasis." (PMID 37259155, 2023). "Little is known regarding the epigenetic regulation of ICOS in melanoma." (PMID 37259155, 2023). "We further corroborated melanoma cell-intrinsic ICOS expression at protein level via IHC." (PMID 37259155, 2023). "In order to exclude that this signal might originate from contaminating non-melanoma cells within the CD45− cell fraction, we analyzed ICOS mRNA expression in N = 33 melanoma cell lines obtained from GDSC." (PMID 37259155, 2023). "Moreover, we found significant correlations between ICOS mRNA with AXL and MITF mRNA expression in the melanoma cell lines from the GDSC (ICOS/AXL: ρ = -0.457, P = 0.008; ICOS/MITF: ρ = 0.441, P = 0.010; N = 33)." (PMID 37259155, 2023). "We recently described a nuclear expression of ICOS in melanoma, however, the biological significance remains unclear." (PMID 37415208, 2023). "Finally, we tested the independency of ICOS CpG 4/5 methylation and ICOS mRNA as biomarkers in melanoma." (PMID 37259155, 2023). "Besides immunotherapy with CTLA4 and PD1 inhibitors, we have recently reported the efficacy of targeting the inducible T-cell co-stimulator (ICOS)/ICOS ligand (ICOS-L) dyad in mouse models of melanoma." (PMID 36500861, 2022). "Furthermore, in melanoma, sargramostim and ipilimumab combination therapy increased overall survival (OS) and enhanced expression of inducible T-cell co-stimulator (ICOS) on CD4+ and CD8+ T cells over ipilimumab alone." (PMID 36685591, 2022). "High-dose IL-2 therapy increased the expansion of the ICOS+ Treg population, which may predict clinical outcomes in melanoma." (PMID 35585567, 2022). "Additionally, concomitant CTLA-4 blockade and ICOS engagement by tumor cells that express ICOSL significantly improved rejection of established melanoma and prostate cancer in mice." (PMID 33777008, 2021). "Increased proliferation of ICOS+ Tregs is also found in melanoma patients after IL-2 therapy." (PMID 34806028, 2021).
melanoma (continued). "Moreover, an enhanced expansion of ICOS+ Tregs in patients with melanoma after the first cycle of high-dose IL-2 therapy was identified to be associated with unfavorable prognosis." (PMID 32983168, 2020). "Indeed, a 4–5-fold increase in Tregs was documented in melanoma patients post HD IL-2 therapy, and increased expansion of ICOS+ Tregs correlated with disease progression in these patients." (PMID 32005826, 2020). "Moreover, an enhanced frequency of melanoma-infiltrating ICOS+ CD4+ T cells, sustained over 3 months of anti-CTLA-4 treatment, was associated with better OS." (PMID 32194568, 2020). "Analysis of patient samples suggested a role for ICOS in the activity of anti-CTLA-4 therapy, including in melanoma patients treated with ipilumumab, where a sustained increase in the frequency of ICOS hi CD4+ T cells correlated with clinical benefit and improved survival." (PMID 32970735, 2020). "Meta-analysis of associations between pretreatment melanoma and NMSC tumors was significant for the combined ASA and cell cycle scores (P = 0.0072 and P = 0.0036, respectively) and for many cGEPs (for example, CellCycle-Late-S, exhaustion, ICOS/CD38; P < 0.05 all)." (PMID 40903640, 2025). "However, some melanomas exhibit ICOS mRNA expression, which correlated with CpG 4/5 methylation." (PMID 37259155, 2023). "Since T cells are the main source of ICOS mRNA and CpG 2 methylation showed the strongest negative correlation with mRNA expression levels in the heterogeneous tumor tissue, we expect lower methylation levels in T cells compared to other immune cells and melanoma cells." (PMID 37259155, 2023). "We observed higher proportions of circulating iNKT cells expressing ICOSL, PD-L2, ICOS, TIM3, and 4-1BB in melanoma patients compared with HDs." (PMID 41562072, 2025). "We generated a surface protein metric called surface TCR.strong based on the geometric mean of OX40 and ICOS MFI, the transcripts of which we have previously reported to be enriched in melanoma patient responders to Nivolumab." (PMID 40351814, 2025). "In prior studies, we demonstrated synergistic increased tumor protection with the concurrent activation of the ICOS pathway and CTLA-4 blockade in mouse melanoma and prostate cancer models." (PMID 38517331, 2024). "In the present study, we comprehensively investigated ICOS DNA methylation and mRNA expression with regard to clinicopathological and immune parameters, survival, and response to ICB in melanoma." (PMID 37259155, 2023). "In patients with bladder cancer, breast cancer, non-small cell lung cancer (NSCLC), and melanoma treated with anti-CTLA-4 immunotherapy, increased levels of ICOS+CD4+ T cells in tumor tissue and peripheral blood were detected." (PMID 37259155, 2023). "We found that ICOS gene expression was enriched in several tumor indications, including HNSCC, lung carcinoma, melanoma, and bladder cancer." (PMID 37593752, 2023). "PD-1 and ICOS coexpression was particularly noteworthy in HNSCC, but was also observed in esophageal cancer, lung cancer, and melanoma." (PMID 37593752, 2023). "After C57BL/6 mice were challenged with freshly prepared B16-F10 (B16) melanoma cells or vehicle controls (PBS), the expression of ICOS, ICOSL and CD28 in the lung was assessed 2 weeks later." (PMID 36618349, 2022). "We noted decreased expression of ICOS and ICOSL in lungs with melanoma metastasis compared to vehicle controls." (PMID 36618349, 2022). "Here we demonstrate that CHI3L1 inhibits the expression of ICOS, ICOSL and CD28 while stimulating CTLA-4 and the B7 moieties in melanoma lung metastasis." (PMID 36618349, 2022). "Studies were undertaken to determine if the expression of T cell co-stimulators such as ICOS and ICOSL was altered by the melanoma lung metastasis." (PMID 36618349, 2022). "Also, ICOSL-expressed by melanoma cells may induce the increased ICOS expression in Treg." (PMID 31143539, 2019).